BCL6 (BCL6 transcription repressor)
Diseases named in the same sentence as BCL6 in open-access papers (continued):
Sharing a sentence is not in itself a finding about the gene and the disease.
influenza (16 papers, 2010 to 2024). An acute viral infection of the respiratory tract, occurring in isolated cases, in epidemics, or in pandemics; it is caused by serologically different strains of viruses (influenzaviruses) designated A, B, and C, has a 3-day incubation period, and usually lasts for 3 to 10 days. "We next analyzed I-Ab:gp66-77 tetramer+ CD4+ T cells for CXCR5, PD-1, and BCL6 expression following influenza infection in medLN to determine the kinetics of memory antigen-specific Tfh cells." (PMID 39283916, 2024). "While influenza cases were primarily characterized by pro-inflammatory signaling and classical anti-viral response gene expression (e.g., BCL6, DLL4, GDF15, PTX3,HMGB2, and IL-8)." (PMID 36371548, 2023). "In a murine model of influenza infection, IL-2 was shown to inhibit Tfr development via inhibition of Bcl-6 and upregulation of Blimp-154." (PMID 35790728, 2022). "Commercial anti-human/mouse BCL6 antibodies were screened for cross-reactivity against ferrets by staining LN cell suspensions recovered from influenza infected ferrets." (PMID 33479388, 2021). "Moreover, BCL6 has been observed to be involved in live-attenuated influenza vaccine (LAIV)-induced T follicular helper cell differentiation, influencing the antibody response." (PMID 39035772, 2024). "Along the same line, ANAs were generated in Bcl6 FC mice after influenza infection." (PMID 36754569, 2023). "Observations from another study using a mouse model of influenza infection reported that expression of transcriptional regulator B cell lymphoma 6 (BCL6) is upregulated in neutrophils that have migrated to the influenza affected lung, possibly to repress neutrophil apoptosis." (PMID 34572056, 2021). "Interestingly, primary Blimp-1−/− anti-influenza CTLs expressed lower levels of T-bet transcripts and increased levels of Eomes and Bcl6 transcripts." (PMID 20333242, 2010). "At 42 days after influenza infection, the PR8(1°) group had maintained a significantly higher frequency of both PD-1- and BCL6-expressing Tfh cells similar to the effector timepoint." (PMID 39283916, 2024). "We found two commercial anti-BCL6 antibodies (clone K112-91 and clone IG191E/A8) had cross-reactivity with lymph node cells from influenza-infected ferrets." (PMID 33479388, 2021). "Although the numbers of BCL6-expressing CXCR5+ GC Tfh cells were highest in LCMV-primed mice, the amount of BCL6 expression in tetramer+ CXCR5+ cells was significantly lower than in both GP-primed mice and after primary influenza infection." (PMID 39283916, 2024). "Contrary, T cell-independent TNP-FICOLL or influenza-immunized mice showed increased but not decreased Bcl6 levels following ethanol or acetate feeding." (PMID 32332730, 2020). "We found that heterologous influenza rechallenge resulted in significant increases in the numbers of polyclonal effector antigen-specific CXCR5– Th1 cells in both rGP- and LCMV-primed mice, as well as CXCR5+BCL6+ GC Tfh cells in LCMV-primed mice compared to primary influenza infection." (PMID 39283916, 2024). "Trim37 prolongs the stability of Bcl6 dependent on its E3 Ub ligase activity, while Trim37 mutant mice carrying the enzymatically inactive Trim37C18R display a diminished ability to differentiate into TFH cells and an insufficient production of anti-influenza high-affinity antibodies." (PMID 37528081, 2023). "We found that IL-21hi cells exhibited the highest expression levels of Il21, Bcl6, and Cxcr5 but not Foxp3, compared with other cell populations, suggesting that TRH cells but not regulatory T cells express IL-21 in the lung after influenza infection." (PMID 38345472, 2024).
autoimmune disease (15 papers, 2014 to 2025). A disorder resulting from loss of function or tissue destruction of an organ or multiple organs, arising from humoral or cellular immune responses of the individual to their own tissue constituents. "Several compounds have been developed to block BCL6 activity in the setting of B cell malignancies and autoimmune diseases, including peptides and small molecule BCL6 inhibitors." (PMID 41246349, 2025). "The potential usefulness of a BCL6 inhibitor for some types of malignant and autoimmune disease has led several groups to develop approaches to perturb the cellular function of BCL6 with the ultimate aim of producing novel therapeutic agents." (PMID 34274316, 2021). "This all is in line with the fact that fully developed eLFs with FDCs, compartmentation into a light and dark zone, an excess of GC-B cells over TFHs as well as the presence of “true”, i.e., active CD4+CXCR5+BCL-6+ TFHs are rare in human autoimmune diseases." (PMID 32010141, 2019). "Ratios of Bcl-6 to Blimp1 transcription factors are lower for Tph than Tfh and Tph have been suggested to drive extrafollicular differentiation of age-related B cells in autoimmune disease." (PMID 40293219, 2025). "Theoretically, as a key transcription factor governing Tfh/Tfr differentiation, BCL6 degraders may be a potential therapeutic option by targeting Tfh cells in the treatment of autoimmune diseases." (PMID 37187757, 2023). "Mechanistically, BCL6 contributes to lymphomagenesis by promoting the survival and proliferation of GC B cells and preventing premature terminal differentiation into memory or plasma cells, which can be beneficial for autoimmune diseases." (PMID 37187757, 2023). "CD4+ CCR9+ T helper cells express high amounts of interleukin 21 and induce T cell costimulatory factor, transcription factor B cell CLL/lymphoma 6 (Bcl-6), and Maf, which are local features of autoimmune diseases that affect the accessory organs of the digestive system." (PMID 34490243, 2021). "Hence, BCL6 degrader treatment may be a double-edged sword in autoimmune diseases and needs further basic and clinical research." (PMID 37187757, 2023). "BCL6, BCL6 transcription repressor or B-cell CLL/lymphoma 6, is a sequence-specific DNA-binding protein that inhibits transcription through interactions with various corepressors and has been extensively studied in autoimmune diseases and cancer." (PMID 36582740, 2022). "Furthermore, while Bcl6-expressing cells do not normally express Teff cytokines, some studies indicate that Tfh cells can produce effector cytokines in the context of high inflammatory conditions, such as viral infections or autoimmune diseases." (PMID 33986755, 2021).
glioma (15 papers, 2018 to 2025). A benign or malignant brain and spinal cord tumor that arises from glial cells (astrocytes, oligodendrocytes, ependymal cells). "Occasionally the BCL6 locus is translocated in glioma, with BCL6 expressed in association with the IDH1 mutation R132H." (PMID 32320427, 2020). "However, whether the high expression of BCL6 in glioma is associated with invasion and chemosensitivity remains unclear." (PMID 30420967, 2018). "In this study, we identified the key role of BCL6 in promoting the proliferation of glioma cells and the progression of glioma." (PMID 40821118, 2025). "To further confirm the overexpression of BCL6 in glioma, we determined the expression level of BCL6 in glioma cells from multiple individuals through western blotting." (PMID 40821118, 2025). "The results revealed that a low concentration of YK01 significantly inhibited clonal formation and invasion of glioma cells with high expression of BCL6." (PMID 40821118, 2025). "In a novel approach, the introduction of miR-144-3p, which targets BCL6, was able to suppress the proliferation and invasion of glioma cells." (PMID 39456751, 2024). "In turn, BCL6 is known to be a glioma-promoting gene and a biomarker whose activation correlates with the clinical grade." (PMID 36231068, 2022). "TF BCL6 in OPC has been uncovered to encourage glioma and also to be a promising target to treat this cancer." (PMID 34976314, 2022). "PAX6, BCL6, HOXD13, and FOX2 have also been shown to be associated with glioma in previous studies 48-50." (PMID 33537074, 2021). "Further, BCL6 overexpression has pro-survival and proliferative activities of glioma cells; its expression in monocytes/macrophage lineage reduces the antitumor immune response and increases the immunosuppressive microenvironment." (PMID 34539626, 2021). "To investigate the role of BCL6 in progress of malignant gliomas, we reduced BCL6 expression by transfecting shBCL6 plasmid into the human glioma cell lines U87 and U251." (PMID 30420967, 2018). "To further investigate the mechanism related to BCL6 promoting malignant phenotype of glioma, we detected the protein level of t-ERK, p-ERK, t-AKT, and p-AKT." (PMID 30420967, 2018). "We performed the cell viability assay and colony-formation assays to observe the effect of BCL6 on the glioma cell proliferation." (PMID 30420967, 2018). "The BCL6 expression in glioma was higher than in normal brain tissues, and the mRNA level of BCL6 significantly elevated in the high-grade glioma samples compared with the low-grade samples." (PMID 30420967, 2018). "Transfection efficiency was confirmed by real-time PCR and western blot analysis of BCL6 levels in the transfected glioma cells." (PMID 30420967, 2018). "By analyzing the expression of BCL6 via RNA sequencing in central nervous system cells in the Cancer Cell Line Encyclopedia database and The Cancer Genome Atlas database, we found that the expression of BCL6 was relatively high in glioma cell lines." (PMID 40821118, 2025). "The glioma tissues also showed a higher level of BCL6 protein than the normal brain tissues." (PMID 30420967, 2018). "This study was to detect the expression of BCL6 and its biological effect on glioma." (PMID 30420967, 2018). "Our results indicated that BCL6 may be a tumor oncogene involved in the progression of glioma via affecting AKT and MAPK signaling pathways." (PMID 30420967, 2018).
glioma (continued). "The overexpression of this gene was correlated with poor survival of the patients with neuroblastoma, and another study suggested that frequent translocation of BCL6 could induce the overexpression of BCL6 and inhibit the apoptosis of glioma cells." (PMID 30420967, 2018). "To identify the expression of BCL6 in glioma, we detected its levels in tissues and cell lines." (PMID 30420967, 2018). "Similarly, the expression of BCL6 got intense along with the advance of glioma grades." (PMID 30420967, 2018). "These resulted suggested that BCL6 might play a critical role in G1-S transition in glioma." (PMID 30420967, 2018). "Thus, the identification of BCL6 may help us to understand the potential molecular mechanisms of the initiation and progression of glioma and provide us with a new prognostic marker for the management of glioma." (PMID 30420967, 2018). "In our study, we found that the reduction of BCL6 expression increased chemosensitivity of glioma cells to TMZ, and the apoptosis rates were upregulated in the reduction of BCL6 expression with TMZ group." (PMID 30420967, 2018). "Studies suggest that inhibiting BCL6 and BCL2 expression may serve as a therapeutic target for central nervous system cancer." (PMID 40520536, 2025). "Our results show that BCL6 is expressed at a high level in glioma when compared with nontumor brain tissues." (PMID 30420967, 2018). "Thus, BCL6 restoration approach may offer a new strategies and tactics to reverse or overcome multidrug resistance and hence to enhance the efficacy of TMZ treatment in glioma is one of the significant mission." (PMID 30420967, 2018).
lung carcinoma (15 papers, 2014 to 2025). "The fact that BCL6 functions as a protooncogene and is required for malignant transformation prompts us to speculate that BCL6 may be linked to oncogenic responses in lung cancer." (PMID 36377663, 2022). "Further studies are required to find the association between BCL6 and lung cancer metastasis." (PMID 25009651, 2014). "For instance, in lung cancer, BCL6 is regulated by the MAPK/ELK1 axis and facilitates KRAS‐driven tumorigenesis." (PMID 41438489, 2025). "Among all the tested genes, the top-performing ones were NUMA1 and JAK1 in KIRC, PDGFRB and BCL6 in lung cancer, IRS2 in endometrial cancer, and GNAS in BRCA, each with an AUC of at least 0.89." (PMID 38491101, 2024). "Our results showed that BCL6 inhibition exerted little effect on ROS production in KRAS-mutant lung cancer cells, thus excluding the role of ROS in BCL6-mediated tumor-promoting action in the context of KRAS mutational activation." (PMID 36377663, 2022). "Analysis of TCGA database showed that ELK1 expression levels were positively correlated with BCL6 expression levels in human lung cancers." (PMID 36377663, 2022). "To uncover the link between BCL6 expression and clinical outcomes in KRAS-mutant lung cancer, we further examined BCL6 expression in human LUAD tissue, including KRAS-mutant subgroup (n = 62) and KRAS WT subgroup (n = 67)." (PMID 36377663, 2022). "Our in vivo studies showed that inhibition of BCL6 transcriptional activity by COMP7 significantly impeded the growth of KRAS-mutant lung cancer cells in preclinical mouse models." (PMID 36377663, 2022). "To test this possibility, we analyzed the cell cycle progression in KRAS-mutant lung cancer cells after BCL6 depletion alone or in combination with BCL6 reconstitution." (PMID 36377663, 2022). "Our recent work additionally revealed that an increased expression of BCL6 largely contributes to the resistance of KRAS-mutant lung cancer to clinical BET inhibitors." (PMID 35503721, 2022). "As reported in our recent work, BCL6 activation attenuated the antitumor efficacy of clinical BET inhibitors in KRAS-mutant lung cancer." (PMID 35503721, 2022). "Collectively, our results suggest that the MAPK/ERK signaling axis promotes BCL6 expression in KRAS-mutant lung cancer cells." (PMID 36377663, 2022). "In summary, our findings reveal a crucial role of BCL6 in promoting KRAS-addicted lung cancer and suggest BCL6 as a therapeutic target for the treatment of this intractable disease." (PMID 36377663, 2022). "Our in vitro and in vivo pharmacological studies collectively demonstrate that BCL6 serves as a potential therapeutic target for the treatment of KRAS-mutant lung cancer." (PMID 36377663, 2022). "Although little has been known for the oncogenic role of BCL6 in epithelial malignancies, a recent study reported that microRNA-187-3p inhibited lung cancer development by targeting oncogenic BCL6." (PMID 27248820, 2016). "BCL6 has been shown to promote the development and maintenance of tumor-associated stem/progenitor-like CD8+ T cells associated with the persistence of anti-tumor responses, providing sustained anti-tumor immunity in the context of lung cancer and melanoma." (PMID 39456751, 2024). "For example, BCL6 overexpression promoted metastasis in lung cancer." (PMID 37060074, 2023). "Given that BCL6 elicits transcriptional activity and directly regulates multiple target genes, we hypothesized that BCL6 plays a role in lung cancer." (PMID 36377663, 2022). "Importantly, BCL6 depletion impeded lung tumorigenesis in a genetically engineered KrasG12D-driven mouse model, and pharmacological inhibition of BCL6 consistently reduced the growth of KRAS-mutant lung cancer cells and prolonged mouse survival." (PMID 36377663, 2022). "Here, we identify B cell lymphoma 6 (BCL6) as a lynchpin in KRAS-driven lung cancer." (PMID 36377663, 2022).